GSK3B (glycogen synthase kinase 3 beta)
Diseases named in the same sentence as GSK3B in open-access papers (continued):
Sharing a sentence is not in itself a finding about the gene and the disease.
Insulin resistance (226 papers, 2006 to 2026). Increased resistance towards insulin, that is, diminished effectiveness of insulin in reducing blood glucose levels. "Studies have shown that the dysregulation of GSK-3β is associated with the development of insulin deficiency and insulin resistance, as well as abnormal tau phosphorylation leading to the toxicity of neurofibrillary tangles (NFT)." (PMID 38660514, 2024). "In hyperglycemic states associated with insulin resistance, GSK3β is overactivated, which impedes glycogen synthesis." (PMID 36976988, 2023). "Our findings indicate that high doses of rosuvastatin impair BCAA catabolism and causes systemic insulin resistance, which is associated with the PP2Cm‐mediated inhibition of Akt and GSK3β signaling pathways." (PMID 37139700, 2023). "Persistent hyperglycemia can lead to insulin resistance in type 2 diabetes, and previous studies have demonstrated that GSK-3β is strongly associated with the development of insulin resistance." (PMID 37513479, 2023). "Low levels of insulin or IGF-1 and insulin resistance cause the inhibition of Akt phosphorylation and subsequent reductions in phosphorylated GSK3β, resulting in the degradation of β-catenin proteins." (PMID 37569816, 2023). "Our data showed an increase in active GSK3β in ECs after the insulin resistance, which was associated with a concurrent increase in VCAM1 and ADAM10 and 17 expressions." (PMID 37762417, 2023). "Therein, the PI3K/AKT/GLUTS/GSK-3β pathway is a major pathway of insulin signaling transduction and an important pathway of blood glucose regulation, which is closely associated with insulin resistance-related diseases." (PMID 37091861, 2023). "Dysfunction of PI3K/Akt/GSK‐3β signaling pathway will not only lead to insulin deficiency and insulin resistance in DM patients, but also lead to tau hyperphosphorylation in the brain of AD patents." (PMID 35445545, 2022). "GSK3β is therefore involved in both insulin resistance and insulin deficiency, two main defects at the origin of T2D pathogenesis." (PMID 36499613, 2022). "Studies have shown that overexpression of GSK-3β causes hypoactivity of its downstream substrate, glycogen synthase, and synthesis of abnormal glycogen, which leads to insulin resistance." (PMID 36506575, 2022). "Insulin resistance can increase levels of advanced glycation end products (AGEs), which cause upregulation of GSK-3β and activation of NF-κB pathway, thus induces ROS and pro-inflammatory cytokine production." (PMID 35173531, 2022). "Insulin resistance is associated with the modulation of amyloid production, tau phosphorylation and neuroinflammation through the regulation of GSK3β activity." (PMID 34627204, 2021). "Curcumin decreased plasma levels of GSK-3β, overexpression of which is associated with insulin resistance, in subjects at risk of developing T2DM." (PMID 34970150, 2021). "Oxidative stress associated with insulin resistance also dysregulates glycogen synthase kinase 3-β (GSK-3β), which leads to increased tau phosphorylation." (PMID 34349617, 2021). "More importantly, GSK-3β is one of the key factors contributing to insulin deficiency and insulin resistance." (PMID 33406505, 2020). "GSK3β has been implicated in mediating the development of insulin resistance, mainly by inhibition of glycogen synthesis." (PMID 33043040, 2020). "Overexpression of GSK3B has been implicated in insulin resistance, polycystic ovary syndrome (PCOS), platinum-resistance in ovarian cancer." (PMID 33133155, 2020). "The primary finding of this study is that oral supplementation with curcumin (180 mg per day) for 12 weeks reduces the circulating levels of peptides that are implicated in insulin resistance, namelt GSK-3β and IAPP." (PMID 32283762, 2020). "GSK3β has also been implicated in the development of insulin resistance and in death of pancreatic beta cells in models of type 2 diabetes." (PMID 30978208, 2019).
Insulin resistance (continued). "GSK3β expression and activity were shown to be increased in muscle of diabetic patients and was implicated in muscle insulin resistance." (PMID 31293498, 2019). "Brain insulin resistance is characterized by increased activation of GSK3β and JNK, two critical kinases implicated in IRS1 inhibition." (PMID 29736736, 2019). "This is in line with previous outcomes showing that in the skeletal muscle of GK rats pAkt was unable to phosphorylate GSK-3β, because both signaling proteins were already highly phosphorylated, which was strongly associated with insulin resistance." (PMID 31623226, 2019). "Of interest, a previous study in diabetic mice also reported that salidroside ameliorated insulin resistance through activation of a mitochondria-associated AMPK/PI3K/Akt/GSK3β pathway." (PMID 28255329, 2017). "GSK-3β impairs the ability of insulin to activate glucose disposal and over-expression is associated with insulin resistance." (PMID 24520329, 2014). "Chronic orexin deficiency disrupts Akt/GSK3β signaling, leading to systemic insulin resistance." (PMID 41438219, 2025). "Dysregulation of GSK3β has been associated with insulin resistance and the development of DKD." (PMID 40526103, 2025). "Dysregulation of GSK-3β is associated with insulin resistance." (PMID 39458839, 2024). "The results demonstrate insulin resistance, further aggravated by PP1γ, caused AD-like phenotype however, through a phenomenon of oppositely regulating phosphorylation of GSK3α and GSK3β isoforms wherein one promotes AD-like phenotypes while the other prevent it." (PMID 37085815, 2023). "Increased GSK3β activation has also been linked to glucose intolerance and insulin resistance, which may explain phenotypes observed in male 6JRccEnv animals." (PMID 37531359, 2023). "In addition, some insulin‐signaling proteins, such as p70S6K, p‐GSK3β, p‐Akt, and p‐insulin receptor, are contained in serum sEVs, indicating its association with incidences of insulin resistance." (PMID 37593852, 2023). "Individuals with ApoE4 may be at increased risk for insulin resistance, and downstream GSK3β/tau kinase I hyperactivity." (PMID 33921683, 2021). "Dietary supplementation with curcumin reduced circulating levels of IAPP and GSK-3β, thus suggesting a novel mechanism through which curcumin could potentially be used for alleviating insulin resistance related markers for reducing the risk of T2D and AD." (PMID 32283762, 2020). "Notably, the high expression of GSK-3β is correlated with insulin resistance and insulin deficiency." (PMID 33406505, 2020). "Takashima22 reported that tau hyperphosphorylation via GSK-3β was associated with insulin resistance in the central nervous system; this suggested, as implied by our study, that impaired brain insulin signaling could contribute to tau hyperphosphorylation." (PMID 29673239, 2018). "TS pathology is caused by mutations in tuberous sclerosis complex (TSC) genes and is associated with insulin resistance, decreased glycogen synthase kinase 3β (GSK3β) activity, activation of the mammalian target of rapamycin complex 1 (mTORC1), and subsequent increase in protein synthesis." (PMID 28646232, 2017). "Moreover, doxorubicin can decrease expression of genes (IRS1, Glut4, AMPK, and GSK3b) involved in insulin signaling in muscle tissues and thus can cause systemic insulin resistance, thus leading to the development of type 2 diabetes-like condition." (PMID 26089893, 2015). "Furthermore, in knockout mice expressing a brain-restricted insulin receptor deficiency (NIRKO) brain insulin resistance impairs insulin-mediated activation of either the PI3K/Akt/GSK-3β or MAPK/ERK pathways in cerebellar granule cells." (PMID 22383997, 2012). "This increases the phosphorylation of IRS1, PI3K, AKT, and GSK3β, while decreasing the phosphorylation of GS, thereby enhancing the transmission of insulin resistance signaling pathways in liver cells." (PMID 41497732, 2026).
Insulin resistance (continued). "Kaempferol derivatives can increase the phosphorylation levels of p‐AKT and its downstream GSK3β, thereby increasing glycogen synthesis and alleviating insulin resistance." (PMID 41551995, 2026). "Both glucolipotoxicity and insulin resistance contribute to GSK3β overactivation, leading to β-catenin phosphorylation and subsequent proteasomal degradation." (PMID 40274715, 2025). "Unexpectedly, the unphosphorylated GSK-3β protein level was higher, suggesting a distinct role for overall GSK-3β in insulin resistance." (PMID 39761309, 2025). "This overactivated GSK3β can then phosphorylate insulin receptor substrate 1 (IRS1) at the Ser332 site, impairing insulin signaling and contributing to insulin resistance, a condition often associated with diabetic nephropathy." (PMID 40526103, 2025). "The findings demonstrated that JWQZG effectively reduces hepatic lipid accumulation and inflammation while improving insulin resistance through activation of the IRS1/PI3K/AKT/GSK3β pathway." (PMID 40221773, 2025). "It is widely accepted that ROS can enhance the impairment of the IRS-1/PKB/GSK3β signaling and promote the phosphorylation of IRS at Ser residue, which is associated with insulin resistance." (PMID 40806739, 2025). "Insulin resistance has been described to elevate the levels of Aβ1-42 and p-Tau and decrease p-GSK3β (Ser9) protein content." (PMID 41154783, 2025). "This regulation affects key proteins involved in hepatic glycogen synthesis, including glycogen synthase kinase-3 beta (GSK3β) and glycogen synthase (GS), ultimately contributing to insulin resistance." (PMID 40599550, 2025). "ECG also functioned against the actions of OA via induction of p-Tyr-IRS-1/PKB/GSK3β pathway, subsequently reducing the insulin resistance by scavenging ROS and targeting AMPK." (PMID 40806739, 2025). "It has been shown that insulin resistance impairs the inhibition of glycogen synthase kinase 3 beta (GSK3β), which is involved in the hyperphosphorylation of tau." (PMID 39358806, 2024). "AKT1 signalling blocks the inhibitory effect of GSK3β on GS, and activated GS enables glycogen synthesis to reduce the production of endogenous glucose and alleviate insulin resistance." (PMID 39568571, 2024). "In the present study, we observed an elevation in gene expression and protein levels of GSK3β – as a marker of insulin resistance – following 6-OHDA injection." (PMID 39830652, 2024). "The findings suggest that 6-OHDA induces neurodegeneration via activation of TLR4 and GSK3β, indicating insulin resistance, and that insulin can improve these impairments." (PMID 39830652, 2024). "The present study provides evidence supporting the idea that hyperinsulinemic condition causes neuronal insulin resistance, as indicated by the downregulation of insulin signalling molecules, including PI3K/AKT, with the upregulation of GSK-3β and TTBK1." (PMID 38536493, 2024). "Increased levels and activity of GSK3β have been observed in insulin resistance and other pathological conditions." (PMID 39830652, 2024). "Conversely, insulin resistance activates GSK3β signaling and enhances arterial TMEM16A channel expression." (PMID 38581667, 2024). "In the state of insulin resistance, the inhibition of downstream insulin signal transduction activates GSK3β; thus, glycogen production is attenuated." (PMID 37569816, 2023). "The activation of GSK3β in ECs after insulin resistance upregulates VCAM1 expression, and VCAM1’s ectodomain is cleaved by the metalloproteases ADAM10 and ADAM17, which also show increased expression in diabetic ECs." (PMID 37762417, 2023). "Brain insulin resistance that is featured by decreased PI3K-Akt activity is also reported to trigger the phosphorylation of Tau by the disinhibition of GSK3β activities and the suppression of Tau phosphatases." (PMID 37511207, 2023).
Insulin resistance (continued). "Here, we have uncovered that insulin resistance leads to the activation of GSK3β in mesenteric artery endothelial cells, which upregulates VCAM1 expression." (PMID 37762417, 2023). "Our data demonstrate that TAC/MSC improved palmitic acid (PA)-induced insulin resistance in HepG2 cells through activating the phosphoinositide 3-kinase (PI3K) /protein kinase B (AKT)/glycogen synthase kinase 3 beta (GSK3β) pathway." (PMID 37513373, 2023). "Participants with prediabetes who consumed 180 mg of curcumin daily had significantly reduced GSK3β and IAPP in serum samples after 12 weeks compared with placebo groups, reducing insulin resistance and the risk of developing AD and DM." (PMID 36909158, 2023). "SFFs also promoted the AKT-1 expression, which in turn inhibited GSK-3β expression and reduced insulin resistance." (PMID 35873798, 2022). "The glycogen synthase kinase-3beta (GSK-3β) in insulin resistance inactivates glycogen synthase (GS) phosphorylation, resulting in a decrease in glycogen synthesis." (PMID 36295064, 2022). "Increased GSK3β activity was observed in peripheral insulin-sensitive tissues, including in the skeletal muscle of T2D patients, thus contributing to insulin resistance." (PMID 36499613, 2022). "They improve insulin resistance by reducing hepatic glucose production and lipid accumulation through the activation of GSK3β and by suppressing both FOXO1 and SREBP transcription." (PMID 36159557, 2022). "In contrast, in the presence of insulin resistance in the body, insulin sensitivity decreases and dephosphorylated GSK-3β increases, resulting in reduced glycogen synthesis and increased blood glucose." (PMID 35845577, 2022). "Inhibited protein expression of GSK-3β and elevation of p-GSK-3β led to stimulation in glycogen synthesis and an improvement in glucose metabolism disorders, thereby alleviating insulin resistance." (PMID 36506575, 2022). "Collectively, insulin resistance induces hyperactivity of GSK-3β, which leads to tau hyperphosphorylation and subsequent PHF-tau and neurofibrillary tangle formation." (PMID 35215222, 2022). "We then investigated the insulin/AKT/GSK3β pathway, which is a central insulin signaling pathway that is attenuated in insulin resistance." (PMID 36477360, 2022). "Studies have shown that oxidative stress inactivates the AKT pathway, followed by increased cerebral insulin resistance, activation of GSK3β, and phosphorylation of tau." (PMID 36430894, 2022). "An inactive GSK3β-induced complex I dysfunction has been reported to promote the ROS production and contribute to insulin resistance." (PMID 36430435, 2022). "Overexpression and overactivation of GSK‐3β in the skeletal muscle tissue are related with the formation of insulin resistance." (PMID 33650786, 2021). "Beyond that in a state of insulin resistance, GSK-3β is restrained by phosphorylation at Ser 9 residue and affect glucose transporter expression." (PMID 34857022, 2021). "Insulin resistance results in the abnormal activation of GSK-3β, and subsequently an increase of tau phosphorylation, leading to neuronal dysfunction in the brain." (PMID 33435277, 2021). "The phosphorylation of AKT was downregulated, and that of GSK-3β was upregulated in neurons under PA-induced insulin resistance." (PMID 33435277, 2021). "Together with the observation in metabolic-imbalanced neurons, our findings reveal that exendin-4 ameliorated insulin resistance through the IRS-1/AKT/GSK-3β pathway in metabolic imbalance in the HFD mouse brain." (PMID 33859286, 2021). "In particular, since the binding of insulin to the insulin receptor (IR) leads to the activation of PI3K/AKT and inactivation of GSK3-β, any disturbance in this transduction pathway will result in insulin resistance." (PMID 34830036, 2021). "A previous study has reported that brain insulin resistance leads to memory loss and inhibits the IRS-1/phosphoinositide 3-kinase/AKT/GSK-3β pathways." (PMID 33859286, 2021).
Insulin resistance (continued). "Insulin resistance and deficiency are increased by abnormally creating insulin signaling through PI3K/Akt/GSK3-β signals; GSK3-β activation is an important component of NFT and can lead to hyperphosphorylated tau." (PMID 34489627, 2021). "Research in hepatic cells demonstrated that AMPK is an upstream target for improving glucose/insulin resistance by regulating Akt/GSK-3β and Akt/PI3K." (PMID 33889593, 2021). "Meanwhile, the phosphorylation of Akt and GSK‐3β significantly increased, resulting in the inactivation of GSK‐3β and the alleviation of insulin resistance." (PMID 33650786, 2021). "They seem to be the most important because phosphorylation of Akt leads to phosphorylation and inactivation of GSK-3β, the enzyme that plays a pivotal role in the final step of glycogen synthesis as well as in the exacerbation of insulin resistance." (PMID 33673122, 2021). "Given that insulin signaling inhibits GSK3β, the lack of the proper intracellular activity mediated by PI3K/AKT suggests that GSK3β would play a deleterious role in neurons after the onset of insulin resistance." (PMID 34356637, 2021). "In our study, PG significantly alleviated HFD induced insulin resistance by enhancing the PI3K/Akt/ GSK3β signaling pathway in the liver." (PMID 32074961, 2020). "The same study observed that GSK3-β activity was correlated with insulin resistance and tau hyperphosphorylation." (PMID 32825356, 2020). "Conversely, inhibition of GSK3β can also regulate glucose levels in animal models of insulin resistance." (PMID 33328854, 2020). "Western blot analysis demonstrated that umbelliferone administration markedly increases the phosphorylation of InsR, IRS-1, AKT, PI3K, and GSK-3β, suggesting an ameliorative effect of umbelliferone against insulin resistance." (PMID 33568996, 2020). "Brain insulin resistance impairs the carbohydrate and fat metabolism to activate GSK-3β by attenuating the phosphorylation of Akt (PKB, protein kinase B) and glycogen-synthase kinase (GSK)-3β." (PMID 32326255, 2020). "In this study, we provided novel insights on the efficacy of curcumin in insulin resistance by providing evidence on regulation of key peptides such as GSK-3β and IAPP, which play an important role in insulin resistance." (PMID 32283762, 2020). "The aim of this study was to determine if dietary supplementation with curcumin reduce plasma levels of peptides, GSK-3β and IAPP that are implicated in the insulin resistance in people at a high risk of developing T2D." (PMID 32283762, 2020). "The results of this study indicated that WS-PE exerted antidiabetic effects by activating Akt/GLUT4 and Akt/GSK3β and further ameliorating insulin resistance, hyperglycemia, and dyslipidemia." (PMID 33061888, 2020). "The results demonstrated that skimmin can obviously upregulate the level of p-PI3K, p-Akt and downregulate the level of GSK3β compared with insulin resistance model group in a dose dependent manner in vitro and in vivo." (PMID 32425786, 2020). "The results revealed that GA inhibited the activation of the phosphorylation of IRS1ser307 and upregulated the expression of AKTser473 and GSK3β in the PI3K/Akt pathway to improve insulin sensitivity under different insulin resistance conditions." (PMID 30871060, 2019). "Inappropriate activation of GSK3β worsens neurodegeneration in patients with AD, brain insulin resistance or T2D." (PMID 31614723, 2019). "Dysregulation of glycogen synthase kinase-3beta (GSK3β) activity has been reported in insulin resistance, T2DM, and neurodegenerative diseases." (PMID 31338065, 2019). "After 14 days in the lipogenic environment, the hepatic spheroids in one donor examined developed insulin resistance as evident from a total reduction of GSK3β phosphorylation and thus a decrease in phos-GSK3β/GSK3β–ratio compared to control time point." (PMID 30250238, 2018).